LCN2 (lipocalin 2)
Diseases named in the same sentence as LCN2 in open-access papers (continued):
Sharing a sentence is not in itself a finding about the gene and the disease.
pancreatic cancer (continued). "At present, although related studies have reported that NUPR1 can inhibit ferroptosis by transcriptionally regulating the expression of LCN2 in pancreatic cancer, promoting the initiation and development of tumours." (PMID 40176685, 2025). "miR-138, although primarily studied in tumor cells, suppresses neutrophil-derived NGAL (lipocalin 2), reducing tumor proliferation and metastasis in pancreatic cancer models." (PMID 40647470, 2025). "LCN2 is also known as a tumor suppressor gene that plays a repressive role in the progression of pancreatic cancer, ovarian carcinoma, and hepatocellular carcinoma." (PMID 40109857, 2025). "In pancreatic cancer, LCN2 expression is correlated with tumor differentiation; well-differentiated and moderately differentiated tissues exhibit strong LCN2 expression, while poorly differentiated tissues are uniformly negative for LCN2." (PMID 40109857, 2025). "LCN2 is highly expressed in the early progression stage of pancreatic carcinoma and ovarian carcinoma, making it a potential marker for early diagnosis and an indicator of malignant transformation." (PMID 40109857, 2025). "Taken together, these findings recently implicate LCN2 as a pathologic mediator of appetite suppression during pancreatic cancer cachexia." (PMID 38397997, 2024). "In a mouse model of pancreatic cancer, Lcn2 is significantly upregulated, its expression correlates with reduced food intake, and Lcn2 deficiency contributes to the prevention of cachexia anorexia." (PMID 39220755, 2024). "Interleukin-1β (IL1B) secreted from neutrophils was reported in pancreatic cancer and was found related to cancer cachexia by induing upregulated expression of LCN2 in the Lcn2-KO mouse model." (PMID 38769374, 2024). "In fact, a recent study found exceedingly increased LCN2 level in the serum and cerebrospinal fluid of the murine models of pancreatic cancer, which is responsible for suppressed appetite and cachexia." (PMID 38035773, 2024). "LCN2 secretion from bone-marrow neutrophils has been reported to mediate appetite suppression during pancreatic cancer cachexia." (PMID 36973755, 2023). "In pancreatic cancer tissues, LCN2 expression was upregulated compared to tissues from healthy individuals." (PMID 36926025, 2023). "Deletion of LCN2 restores appetite in pancreatic cancer-induced cachexia, similarly to the pharmacological inhibition of the MC4R receptor, which reduces anorexia in tumor-bearing mice." (PMID 36078078, 2022). "For example, the relatively poor prognosis of several invasive breast cancer, pancreatic cancer, and colorectal carcinoma is closely related to LCN2 overexpression." (PMID 35989326, 2022). "Increased circulating LCN2 levels were reported in murine pancreatic cancer cachexia models, which potentiated muscle and fat wasting in these models." (PMID 36428623, 2022). "A tumor suppressing role of LCN2 has been found for instance in colorectal or pancreatic cancer, whereas LCN2 promotes tumorigenesis in breast or prostate cancer." (PMID 35053376, 2022). "We observed significantly higher LCN2 protein levels in the lung, liver, and spleen during pancreatic cancer cachexia." (PMID 33824339, 2021). "The purpose of this work was to evaluate the role of LCN2 in mediating the anorectic component of pancreatic cancer cachexia." (PMID 33824339, 2021). "OSCC and pancreatic cancer study reported that high lipocalin-2 expression was related to a longer survival time." (PMID 33542838, 2021). "After observing upregulation of LCN2 in the periphery and CNS of mice that develop pancreatic cancer cachexia, we wanted to determine if genetic deletion of Lcn2 would reverse the behavioral and physiologic manifestations of cachexia." (PMID 33824339, 2021). "Taken together, these findings implicate LCN2 as a pathologic mediator of appetite suppression during pancreatic cancer cachexia." (PMID 33824339, 2021).
pancreatic cancer (continued). "In five separate rodent models of pancreatic cancer cachexia, we demonstrate a large induction of circulating and central LCN2 levels that negatively correlate with food intake and muscle mass." (PMID 33824339, 2021). "Here, we have shown that LCN2 is elevated during pancreatic cancer in humans and mice and induces appetite suppression through its actions in the CNS." (PMID 33824339, 2021). "Based on our data presented here, we propose LCN2 as a potential therapeutic target for the improvement of appetite during pancreatic cancer cachexia." (PMID 33824339, 2021). "Next, we sought to determine if an increase in LCN2 in patients diagnosed with pancreatic cancer corresponded with alterations in fat and lean mass, as these were consistent findings in our rodent models." (PMID 33824339, 2021). "Here, we explore the relationship between LCN2 production, feeding behaviors, and tissue catabolism during pancreatic cancer cachexia." (PMID 33824339, 2021). "Our data show a consistent elevation of circulating and central LCN2 levels in five separate rodent models of pancreatic cancer that induce variable degrees of cachexia." (PMID 33824339, 2021). "In humans, we observe a similar immunologic shift and upregulation of LCN2 during the progression of pancreatic cancer." (PMID 33824339, 2021). "With a 27-fold higher expression in pancreatic cancer cells (compared with normal ductal cells) and an elevated serum level in 94% of the pancreatic cancer patients, LCN2 is reported as an early detection marker for pancreatic malignancies." (PMID 34588926, 2021). "Our data are seemingly consistent with this idea of a prolonged inflammatory state (pancreatic cancer) increasing LCN2 production to regulate appetite." (PMID 33824339, 2021). "In contrast, in mice with diet-induced pancreatic cancer on a LCN2−/− background had fewer and smaller tumors, less inflammation (reduced infiltration of CD45+ leukocyte cells and F4/80+ macrophages) and fibrosis compared to wild-type." (PMID 32328462, 2020). "A subcutaneous mouse model in pancreatic cancer showed that upregulation of LCN2 promotes invasion, tumorigenicity, and gemcitabine resistance." (PMID 32575507, 2020). "LCN2 is also up-regulated in some cancers, including breast, cervical and pancreatic cancer, and LCN2 expression correlates with increased invasiveness and poor prognosis." (PMID 29789480, 2018). "Here, we report that LCN2 contributes to the invasive, angiogenic, and drug resistant phenotypes in pancreatic cancer." (PMID 23056397, 2012). "With respect to angiogenesis, studies of pancreatic cancer cells showed LCN2 to block HUVEC endothelial cells tube formation and reduce VEGF secretion." (PMID 22559235, 2012). "Of the lipocalins, lipocalin-2 (LCN2, also neutrophil-gelatinase associated lipocalin, NGAL) is most relevant to this study since LCN2 suppresses angiogenesis in pancreatic cancer." (PMID 21085487, 2010). "In pancreatic cancer, LCN2 overexpression downregulates VEGF production and inhibits angiogenesis." (PMID 40109857, 2025). "The upregulation of LCN2 has been observed in pancreatic cancer." (PMID 40522948, 2025). "Moreover, elevated LCN2 expression suppressed the progression of pancreatic cancer in an orthotopic mouse model." (PMID 40109857, 2025). "Upon further investigation, it was revealed that LCN2 could serve as a potential therapeutic target, as depletion of LCN2 in a pancreatic cancer mouse model resulted in increased survival." (PMID 40522948, 2025). "LCN2 inhibits pancreatic cancer stemness via the AKT/c-jun pathway." (PMID 38397997, 2024). "Furthermore, a study in a mouse model of pancreatic cancer cachexia revealed that circulating LCN-2 levels were increased in cachectic mice and correlated with anorexia and muscle loss; genetic deletion of LCN-2 ameliorated cachexia-associated anorexia." (PMID 37006254, 2023).
pancreatic cancer (continued). "In conclusion, the present study shows that circulating LCN-2 is associated with neutrophil activation in pancreatic cancer patients, irrespective of their cachexia status." (PMID 37006254, 2023). "Pancreatic tumors were able to induce LCN2 in bone marrow-derived neutrophils." (PMID 36078078, 2022). "Despite the varying degrees of cachexia symptoms (anorexia and muscle catabolism), as well as inflammatory and catabolic gene signatures, we observed increased LCN2 protein in the circulation and cerebrospinal fluid (CSF) in all models of pancreatic cancer cachexia." (PMID 33824339, 2021). "In addition to some inflammation and pathological conditions, the versatile cytokine LCN2 has gained attention as a potential biomarker and a modulator of some human cancers, including breast, thyroid, colon, and pancreatic cancers." (PMID 34202288, 2021). "How is LCN2 modulating iron trafficking in the context of pancreatic cancer?" (PMID 34439145, 2021). "To test whether our observations in these preclinical models of cachexia extend to human disease, we measured plasma LCN2 levels in patients with pancreatic cancer at diagnosis and, in several cases, follow-up visits." (PMID 33824339, 2021). "Finally, after dichotomizing pancreatic cancer patients into high (>240 ng/mL) and low (<240 ng/mL) LCN2 levels at diagnosis, we observed that patients with elevated LCN2 at the time of diagnosis had reduced overall survival." (PMID 33824339, 2021). "Finally, are there permissive factors specific to pancreatic cancer that allow for the anorectic effects of LCN2 during cachexia?" (PMID 34439145, 2021). "Likewise, pancreas cancer cells that overexpressed LCN2 exhibited a reduction in focal adhesion kinase (FAK) tyrosine-397 phosphorylation and vascular endothelial growth factor (VEGF) secretion." (PMID 32575507, 2020). "Moreover, LCN2 expression is increased in neoplastic pancreatic tissue lesions, which typically develop into pancreatic cancer." (PMID 32575507, 2020). "Similarly, LCN2 expression was found to be highly upregulated in human pancreatic cancer tissues and blood compared to pancreas tissue and blood samples of healthy controls." (PMID 32575507, 2020). "LCN2 has also been demonstrated to inhibit invasion and angiogenesis in pancreatic cancer." (PMID 26840566, 2016). "LCN2 was also demonstrated to inhibit invasion and angiogenesis in pancreatic cancer." (PMID 25940797, 2015). "In particular, Lcn2 in microarray and proteomic analysis has been considered as a biomarkers of cancer diagnosis and drug efficacy in the colon of an azoxymethane-induced colon carcinogenesis model and pancreatic cancer of human patients." (PMID 26151867, 2015). "An elevated expression of LCN2 has been observed in pancreatic cancer." (PMID 25476483, 2015). "The relationship between high levels of lipocalin-2 being detected in clinical samples of different tumor types, especially in epithelial origin tumors, such as esophageal, gastric, ovarian, pancreatic cancers with clinical outcomes are being published." (PMID 22640376, 2012). "In pancreatic cancer, BICC1 facilitates metastasis by binding to the mRNA of LCN2, thereby increasing LCN2 expression." (PMID 39717922, 2025). "Although LCN2 reportedly inhibits the late-stage progression of angiogenesis and EMT in pancreatic carcinoma and ovarian carcinoma, respectively, a high LCN2 level in the early stage implies a role for LCN2 in tumorigenesis." (PMID 40109857, 2025). "Several potential mediators were identified in pancreatic cancer, such as LRG1 and LCN2, which can cross the attenuated BBB in the MBH." (PMID 35031523, 2022). "In a gene expression profile study performed with 19 pancreatic cancer cells and the immortalized human pancreatic ductal epithelial cell line (HPDE), LCN2 was one of the genes significantly overexpressed in cancerous versus immortalized cells." (PMID 32575507, 2020).
pancreatic cancer (continued). "Significant elevation in serum concentrations of LCN2 and RBP4 has been observed in pancreatic cancer patients." (PMID 26131602, 2015). "We should emphasize here that the mRNA expression of LCN2, a proinflammatory secretory protein, was robustly increased at the cachexia stage, but not the pre-cachexia stage, after transplantation of pancreatic cancer cells." (PMID 38685046, 2024). "LCN2 treatment has itself resulted into an increased expression of MMP1, MMP3 and MMP9 along with an upregulation of IL-1β, IL-6, IL-8, ICAM-1 and C-X-C motif chemokine 2/monocyte chemoattractant protein 1 (MCP-1) in pancreatic cancer stellate cells." (PMID 34588926, 2021). "Pancreatic cancer study reported that high expression of lipocalin-2 was related to negative lymph node metastasis and earlier TNM stage." (PMID 33542838, 2021). "For example, LCN2 prevented metastasis and epithelial mesenchymal transition (EMT) in hepatocellular carcinoma and was a novel suppressor of invasion and angiogenesis in pancreatic cancer." (PMID 27912767, 2016). "It is likely that these myeloid cells and blood borne biomarkers of pancreatic cancer act in symphony to induce some of the observed local changes in the MBH, which is confirmed by the high level of co-regulation between a number of these transcripts (e.g. lrg1, Plin4, Lcn2 and Icam1)." (PMID 35031523, 2022). "However, we did not observe an increase in bone marrow LCN2 during pancreatic cancer cachexia, potentially owing to a saturating level in both sham and cachexia conditions." (PMID 33824339, 2021). "Furthermore, genetic deletion of Lcn2 did not affect the myeloid to lymphocyte ratio during pancreatic cancer cachexia, demonstrating a similar immunologic profile amongst Lcn2-KO and WT genotypes." (PMID 33824339, 2021). "An orthotopic xenograft mouse model of pancreatic cancer showed a decrease in tumor size, metastatic score, and the expression of the CD31 angiogenesis marker in the LCN2-overexpressing mice group compared to the control group (non-LCN2-expressing pancreatic cancer cells)." (PMID 32575507, 2020). "However, a tissue expression microarray demonstrated intense luminal and cytosolic staining of LCN2 in human pancreatic cancer tissues, whereas normal pancreatic ductal epithelial cells showed no LCN2 expression." (PMID 32575507, 2020). "Rather perplexing though, modulating LCN2 expression in human pancreatic cancer cells did not affect cell viability in vitro, but once engrafted LCN2-overexpressing tumors were smaller, poorly vascularized and had fewer metastases in an orthotopic nude mouse model." (PMID 32328462, 2020). "The other selected genes are HIST1H1E, LRAT, LCN2, KCNN4, RHOU, and EPHA5 in the order of them entering the model, among which LRAT, LCN2, RHOU, and EPHA5 are known to link to prostate cancer, and HIST1H1E and KCNN4 are connected to myeloma and pancreatic cancer, respectively." (PMID 29100492, 2017). "When LCN2 was knockout or its central ligand MC4R was antagonized by agouti‐related peptide, the food intake of these pancreatic cancer mice was restored and the mice did not exhibit cachexia phenotypes." (PMID 38035773, 2024).
renal failure (73 papers, 2012 to 2025). "The neutrophil gelatinase-associated lipocalin 2 (LCN2) is a critical inflammatory mediator persistently induced during endotoxemia, contributing to tubular damage and kidney failure." (PMID 22514649, 2012). "Lipocalin 2 (Lcn 2) also known as Neutrophil Gelatinase-Associated Lipocalin or NGAL is a critical inflammatory mediator, contributing to tubular damage and kidney failure." (PMID 29091707, 2017). "Additionally, kidney failure markers, namely Lcn2 (lipocalin 2), F2rl1 (coagulation factor 2 receptor-like 1), and Plat (plasminogen activator inhibitor-1), were upregulated (Cluster IV)." (PMID 35764881, 2022). "As a consequence, inflammatory mediators such as LCN2 may accumulate and lead to chronic tissue damages including kidney failure." (PMID 22514649, 2012).
COVID-19 (70 papers, 2020 to 2026). A disease caused by infection with severe acute respiratory syndrome coronavirus 2. "Lipocalin-2 and resistin levels were higher in the placenta, revealing an underlying pro-inflammatory status in the gestation period for mothers suffering from COVID-19." (PMID 38610889, 2024). "In this study, we found that a neutrophil-associated host factor LCN2 was significantly elevated and associated with severity in both influenza and patients with COVID-19 by integrated public data analysis." (PMID 35495713, 2022). "Emerging evidence from our study also suggests that lower LCN2 levels might be associated with improved prognosis in severe COVID-19 patients." (PMID 37598150, 2023). "For instance, while reducing the correlation between DEGs including IL10, CXCL8, NFKB1, ARG1, and SOD2, new strong associations appeared between ELANE, DEFA4, AZU1, CTSG, and LCN2, with an overall tendency to higher relationships amid neutrophil-mediated immunity genes in COVID-19 patients." (PMID 35269470, 2022). "For the development of a multivariate prediction model for risk stratification of COVID-19 patients, the established clinical score CRB-65 and biomarkers TnThs, PCT, ET-1, Ang-2, NT-proBNP, copeptin and lipocalin-2 were considered." (PMID 40828447, 2025). "Lipocalin-2 and resistin levels were higher in the placental tissue (p < 0.05 and p < 0.01, respectively) of mothers suffering from COVID-19 compared with the control group." (PMID 38610889, 2024). "Essentially, COVID-19 patients show lower serum iron and higher levels of serum ferritin, hepcidin, and lipocalin-2 compared to controls or the reference range." (PMID 35849261, 2023). "Serum lipocalin-2 levels were higher in symptomatic and asymptomatic COVID-19 patients compared to healthy volunteers/control group." (PMID 35849261, 2023). "Further analyses are required in a larger cohort of patients in order to better validate LTB4 and LCN2 as a potential biomarker for COVID-19 and long-COVID." (PMID 36613462, 2022). "In our work, we measured an increase in circulating plasma LCN2 levels in the cohort of COVID-19 versus long-COVID patients and healthy controls, parallel to the data reported here concerning the protein amounts in PBMCs." (PMID 36613462, 2022). "Given the observation that the cellular and systemic LCN2 forms were significantly elevated in COVID-19 patients, we propose that during SARS-CoV2 infection, an induction of LCN2-mediated protection against iron-induced toxicity can occur." (PMID 36613462, 2022). "They stated that the detection of this protein, in addition to lipocalin 2 and matrix metallopeptidase 8, at high concentrations, in the circulation of critically ill COVID-19 patients strongly suggests neutrophil activation and degranulation." (PMID 35330391, 2022). "We found that LCN2 plasma levels were significantly increased in COVID-19 patients compared with long-COVID patients and healthy donors." (PMID 36613462, 2022). "But the expression of LCN2 was not significantly altered in SARS-CoV (p > 0.05), indicating the possibly unique role of LCN2 in COVID-19." (PMID 33242255, 2020). "Anemia of inflammation, hypoferremia, poor transferrin saturation, and high levels of serum ferritin, hepcidin, lipocalin-2, catalytic iron, and soluble transferrin receptor (in ICU patients) have all been iron-associated changes in COVID-19 from the beginning." (PMID 37763241, 2023). "Interestingly, the results were consistent with those in COVID-19; 27 of the IRGs were highly expressed in myeloid cells, except Icam1, Lyn, Cybb, Casp1, Gbp1, Vnn2, Socs3, Bcl2a1 and Lcn2 genes." (PMID 36817436, 2023). "Interestingly, LCN2 was identified to be upregulated in a COVID-19 specific manner in our analysis across the datasets and was preferentially expressed in that cell population." (PMID 35991542, 2022).